PKD1 (polycystin 1, transient receptor potential channel interacting)
Diseases named in the same sentence as PKD1 in open-access papers (continued):
Sharing a sentence is not in itself a finding about the gene and the disease.
Marfan syndrome (2 papers, 2025). A disorder of the connective tissue. "Each of these disorders has well-established major causative genes: PKD1 and PKD2 for ADPKD, FBN1 for Marfan syndrome, and NF1 for NF1 disease." (PMID 41411243, 2025). "Causative genes include autosomal polycystic kidney disease (PKD1, PKD2), Ehlers–Danlos syndrome (COL3A1), Marfan syndrome (FBN1), Loeys–Dietz syndrome (TGFB2, TGFB3, TGFBR1, TGFBR2, SMAD2, SMAD3), and Majewski Osteodysplastic Primordial Dwarfism (PCNT)." (PMID 40004483, 2025).
mitral valve prolapse (2 papers, 2024 to 2025). A fairly common and often benign valvular heart disorder characterized by redundancy or hooding of mitral valve leaflets so that they prolapse into the left atrium, often causing mitral regurgitation. "Among the 87 genotyped patients, a significant association was found between mitral valve prolapse and PKD1 truncating mutations (pairwise Fisher’s exact test PKD1 truncating versus PKD2 adjusted P-value = .007)." (PMID 41195291, 2025). "Association between mitral valve prolapse and truncating PKD1 mutation." (PMID 41195291, 2025). "Furthermore, our findings link aortic regurgitation directly to markers of renal disease severity and confirm an association between mitral valve prolapse and truncating PKD1 mutations, adding granularity to our understanding of cardiac risk in ADPKD." (PMID 41195291, 2025). "Notably, mitral valve prolapse has been reported in approximately 26% of patients with ADPKD due to PKD1 mutations." (PMID 39009643, 2024). "Among the 20 patients with mitral valve prolapse, 13 (65%) had PKD1 truncating mutations, 5 (25%) had PKD1 non-truncating mutations and 2 (10%) had PKD2 mutations." (PMID 41195291, 2025).
myocardial infarction (2 papers, 2020 to 2022). Gross necrosis of the myocardium, as a result of interruption of the blood supply to the area, as in coronary thrombosis. "Protein kinase D1 (PKD1) mediates the processes of myocardial remodeling, angiogenesis and myocardial contraction, but the mechanism of PKD1 in the processes of the inflammatory response and cell injury in the microenvironment after myocardial infarction has not been determined." (PMID 32411013, 2020).
nephrotic syndrome (2 papers, 2019 to 2023). A collection of symptoms that include severe edema, proteinuria, and hypoalbuminemia; it is indicative of renal dysfunction. "Herein, we report a case of a 23-year-old man with PKD1-associated ADPKD and nephrotic syndrome, whose renal histology showed typical focal segmental glomerulosclerosis (FSGS) and remarkable glomerular cyst formation." (PMID 31455242, 2019).
ovarian carcinoma (2 papers, 2016 to 2024). A malignant neoplasm originating from the surface ovarian epithelium. "Analyzing protein IHC data from the HPA database, we observed elevated expression of PKD1 and NEK6 proteins in ovarian cancer compared to normal ovarian tissue." (PMID 39256367, 2024).
Parkinson disease (2 papers, 2022 to 2024). A progressive degenerative disorder of the central nervous system characterized by loss of dopamine producing neurons in the substantia nigra and the presence of Lewy bodies in the substantia nigra and locus coeruleus. "Furthermore, quercetin treated neurodegenerative dysfunction in the mouse Parkinson's disease model through up-regulating PPARγ, PGC-1α, and TFAM to activate the polycystin 1 (PKD1)/Akt pathway." (PMID 36092543, 2022).
renal carcinoma (2 papers, 2013 to 2023). A carcinoma arising from the epithelium of the renal parenchyma or the renal pelvis. "We also observed binding of HIF-2α in HKC-8, RCC4 and 786-0 cells in the published ChIP-seq data and wondered whether this isoform could contribute to PKD1 regulation under certain circumstances, e.g. in renal cancer, when HIF-2α is released by defective VHL protein." (PMID 37206967, 2023).
Stroke (2 papers, 2017 to 2025). Sudden impairment of blood flow to a part of the brain due to occlusion or rupture of an artery to the brain. "Among these, three are likely monogenic causes of stroke (ELN, SCN5A, and VHL genes), two are considered risk factors (FV and ADAMTS13), two have conflicting interpretations (ACAD9 and ENG), and three are most likely benign (CBS, PMM2, and PKD1)." (PMID 40650005, 2025). "However, after experimental stroke by MCAO, PKD1 KO suffered increased neuronal injury compared to PKD1floxed animals, as determined by Nissl staining and T2-weighted magnetic resonance imaging (MRI)." (PMID 29273751, 2017).
thoracic aortic aneurysm (2 papers, 2023 to 2025). An aneurysm formed in the wall of the proximal portion of the descending aorta proceeding from the arch of the aorta. "Using the ClinGen framework, genes predisposing to heritable thoracic aortic aneurysms and dissection have been identified, though PKD1 and PKD2 mutations are considered risk alleles with limited evidence as a Mendelian cause of heritable thoracic aortic aneurysm and dissection." (PMID 40093803, 2025).
type 2 diabetes (2 papers, 2019 to 2023). "Our data support a positive regulatory role for both P2Y1 and PKD1, particularly in obese (but nondiabetic) donors, suggesting a role for this pathway in compensatory upregulation of insulin secretion and that disruption of P2Y1‐PKD1 signaling may promote β cell dysfunction in type 2 diabetes." (PMID 31591827, 2019).
abdominal aortic aneurysm (1 paper, 2013). Enlargement and ballooning of the vessel that supplies arterial blood to the abdomen, pelvis and legs. "ADPKD-associated vascular manifestations, such as aortic root dilatation, coarctation of aorta, and abdominal aortic aneurysm, are also associated with the mutation in PKD1." (PMID 23840219, 2013).
adenoma (1 paper, 2023). A neoplasm arising from the epithelium. "As major conclusions, this study for the first time directly demonstrates that an intact Pkd1 gene supports early stages of CRC formation, and that loss of PKD1 is tumor suppressive in adenoma formation mediated by loss of APC in a mouse model." (PMID 37542051, 2023). "This study does not assign a single specific signaling mechanism by which loss of PKD1 inhibits CRC, although it excludes inhibition of WNT/CTNNB1 as one possibility, based on elevation of this pathway in Pkd1-mutated murine adenomas or in human tumors bearing somatic PKD1 mutations." (PMID 37542051, 2023).
androgen insensitivity syndrome (1 paper, 2023). Androgen insensitivity syndrome (AIS) is a disorder of sex development (DSD) characterized by the presence of female external genitalia, ambiguous genitalia or variable defects in virilization in a 46,XY individual with absent or partial responsiveness to age-appropriate levels of androgens. "Of these, three patients had variants related to mild androgen insensitivity syndrome, two in genes related to hypogonadotropic hypogonadism, and six in genes related to spermatogenic failure, while one patient is mutant in PKD1." (PMID 37540677, 2023).
aortic aneurysm (1 paper, 2023). A ruptured aneurysm located in the wall of the proximal portion of the descending aorta proceeding from the arch of the aorta. "The process of aortic aneurysm formation in ADPKD has not yet been completely understood; it is speculated that PKD1 haploinsufficiency leads to the upregulation of TGF-ß signaling." (PMID 37443678, 2023).
aortic regurgitation (1 paper, 2025). "This study demonstrates an independent association between LVH and PKD1 mutations and links aortic regurgitation with renal disease severity in ADPKD." (PMID 41195291, 2025). "The independent association of PKD1 mutations with LVH and the link between aortic regurgitation and disease severity provide valuable prognostic information." (PMID 41195291, 2025).
arachnoid cyst (1 paper, 2023). Intracranial or spinal cavities containing a cerebrospinal-like fluid, the wall of which is composed of arachnoidal cells. "In addition, the continuous deletion of the TSC2 and PKD1 genes increases the risk of an arachnoid cyst developing." (PMID 37679848, 2023).
Arthritis (1 paper, 2019). Inflammation of a joint. "In the present study we investigated whether treatments with the pharmacological agent Gö6976, which can suppress TLR/IL-1R-induced PKD1 activity, alter the pathogenic course of an experimental arthritis." (PMID 31809526, 2019). "Our results suggest a possibility that ameliorating effects of Gö6976 on CIA may be due to its ability to inhibit TLR/IL-1R-activated PKD1, which might play an important role in proinflammatory responses in arthritis, and that PKD1 could be a therapeutic target for inflammatory arthritis." (PMID 31809526, 2019). "However, it is completely unknown at this point whether PKD1 plays a protective or a detrimental role during the course of any form of arthritis." (PMID 31809526, 2019). "Although more studies are necessary to sort those issues out, our results support the notion that PKD1 might be a reasonable new target for therapeutic intervention for arthritis, and that pharmacological inhibitors of PKD can be useful therapeutics for inflammatory arthritis, including RA." (PMID 31809526, 2019). "Collectively, our findings imply that the ameliorating effects of Gö6976 on CIA may be due to its ability to inhibit TLR/IL-1R-activated PKD1 that might play an important role in proinflammatory responses in arthritis, and that PKD1 could be a therapeutic target for inflammatory arthritis." (PMID 31809526, 2019). "Collectively, these results imply that PKD1 might be one of the key factors that modulate pathogenesis of certain types of human arthritis, including RA and that activity of TLR/IL-1R-induced PKD1 can be suppressed by Gö6976." (PMID 31809526, 2019). "In addition, the role of PKD1 on the pathogenesis of CIA and other experimental arthritis are currently under investigation using inducible PKD1-gene deficient mice." (PMID 31809526, 2019). "In this study, we investigated whether PKD1 contributes to TLR-mediated proinflammatory responses in human synovial cells, and whether Gö6976 treatment can suppress the development and progression of type II collagen (CII)-induced arthritis (CIA) in mouse." (PMID 31809526, 2019). "Because our results showed that PKD1 is activated and essential for the TLR/IL-1R-induced cytokine and chemokine expression in HFLS isolated from patients with RA, we thought that a pharmacological agent that can inhibit TLR/IL-1R-mediated PKD1 activation may have ameliorating effects on arthritis." (PMID 31809526, 2019).
asthenozoospermia (1 paper, 2022). "The authors analyzed a set of 90 unrelated families with ADPKD and identified predicted pathogenic variants in PKD1 and PKD2 associated with low sperm quality, mainly asthenozoospermia or oligo-astheno-zoospermia." (PMID 35409285, 2022).
astrocytic tumor (1 paper, 2025). A glial tumor of the brain or spinal cord showing astrocytic differentiation. "The aim of the present research study was to investigate the expression of PKD1 and PKD2 in astrocytic tumors and correlate it with clinicopathological characteristics such as the grade of malignancy, age, and gender of the patients." (PMID 40299470, 2025).
astrocytomas (1 paper, 2025). "In the present study, we aimed to investigate the expression of PKD1 and PKD2 and their encoded proteins PC1 and PC2 in astrocytoma samples including GBMs." (PMID 40299470, 2025). "The aim of the present study was to investigate the expression of PKD1 and PKD2 as well as PC1 and PC2 in serial sections of different grades of malignancy astrocytoma samples and compare them with normal brain tissues." (PMID 40299470, 2025). "Both PC1 and PC2 (and their counterpart genes, PKD1 and PKD2) demonstrated significantly increased expression throughout the astrocytoma tissues compared to the normal brain samples." (PMID 40299470, 2025). "Spearman’s correlation analysis revealed a significant relationship between PKD1 and PKD2 expression in astrocytomas included in the study (rho = 0.629, p = 0.01)." (PMID 40299470, 2025). "Gene expression analysis by qRT-PCR revealed significantly increased levels of PKD1 and PKD2 in astrocytomas compared to normal brain tissues (p < 0.05)." (PMID 40299470, 2025). "Additionally, PKD1 expression was significantly higher in WHO, grade IV astrocytomas as compared with WHO, grade II astrocytomas (p < 0.05)." (PMID 40299470, 2025). "In this aspect, the expression of PKD1 and PKD2 in human astrocytomas is largely unknown." (PMID 40299470, 2025).
bipolar disorder (1 paper, 2017). A disorder of the brain that causes unusual shifts in mood, energy, activity levels and the ability to carry out day-to-day tasks. "This gene list includes new excellent candidates with putative links to bipolar disorder, including ADK, GTF2I, hnRNP-A1, HTRA2, PKD1 and RERE, which have been linked to various brain-related diseases." (PMID 28915787, 2017).
brain ischemia (1 paper, 2017). Diminished or absent blood supply to the brain caused by obstruction (thrombosis or embolism) of an artery resulting in neurologic damage. "Cerebral ischemia increased MDA labeling in both genotypes but levels in PKD1 KO registered a robust three-fold increase over those in PKD1floxed brain." (PMID 29273751, 2017).
brain malformation (1 paper, 2022). "However, whether the PKD1 variants were associated with brain malformation warrants further studies with large cohorts and advanced neuroimaging techniques." (PMID 35620448, 2022).
carcinoids (1 paper, 2020). "BP-NENs were characterized by low PKD1 expression, and lung neuroendocrine cancers demonstrated lower PKD1 mRNA levels than carcinoids (p = 0.003)." (PMID 33138224, 2020). "Similarly, the PKD1 mRNA expression has been found to be characteristic for carcinoids and included in the NET-specific transcript set, which could be useful in the diagnostic and monitoring procedures." (PMID 33138224, 2020).
chronic pancreatitis (1 paper, 2020). A chronic inflammatory process causing damage and fibrosis of the pancreatic parenchyma. "Our results clearly indicate that PKD1 expression effectively differentiated PDAC from healthy controls and chronic pancreatitis." (PMID 31819177, 2020). "Thus, in this study, we present the expression profile of PKD1 in human PanINs (early–late), PDAC and chronic pancreatitis tissues and determine its correlation with different tumour differentiation status (well–poorly)." (PMID 31819177, 2020).
colitis (1 paper, 2023). Inflammation of the colon. "Notably, Pkd1 loss increased colon barrier function, with Pkd1-deficient animals resistant to DSS-induced colitis, associated with upregulation of claudins that decrease permeability, and reduced T cell infiltration." (PMID 37542051, 2023).
complex partial seizures (1 paper, 2022). "In the present study, the seven patients with EFS+ and PKD1 mutations had complex partial seizures and/or focal discharges in EEGs, suggesting potential neurodevelopmental abnormalities." (PMID 35620448, 2022).
cortical cysts (1 paper, 2025). "The PKD1 variant was reported to the family, and a renal scan was also recommended for the mother, who was found to have two small cortical cysts." (PMID 41225654, 2025).
diabetic cardiomyopathy (1 paper, 2018). Diabetic cardiomyopathy is a disorder of the heart muscle in people with diabetes. "On the other hand, pharmacological drugs that would specifically induce PKD1 activation might be beneficial for the treatment of the condition of diabetic cardiomyopathy." (PMID 29930945, 2018). "Moreover, PKD2, but not PKD1, auto-phosphorylation is upregulated in hearts of db/db mice, a mouse model of diabetic cardiomyopathy." (PMID 29930945, 2018).
Dolichocephaly (1 paper, 2021). An abnormality of skull shape characterized by a increased anterior-posterior diameter, i.e., an increased antero-posterior dimension of the skull. "Therefore, we firstly sought to determine the mRNA expression of the PKD1 gene in primary cranial suture cells of trigonocephaly and dolichocephaly patients via RT‐PCR." (PMID 33656806, 2021).
Ehlers-Danlos syndrome (1 paper, 2020). The Ehlers–Danlos syndromes (EDS) are a clinically and genetically heterogeneous group of heritable connective tissue disorders (HCTDs) characterized by joint hypermobility, skin hyperextensibility, and tissue fragility. "One case (ScPt0743044L) with a likely pathogenic missense variant in PKD1 has hypermobility with Ehlers-Danlos syndrome-like features, reports easy bruising and has a family history of SCAD (first cousin) and hypermobility (son)." (PMID 33125268, 2020).
endometrial cancer (1 paper, 2022). Primary or metastatic malignant neoplasm involving the endometrium (mucous membrane that lines the endometrial cavity). "The mechanisms underlying PKD1 were associated with apoptosis, B cell receptor signaling pathway, endometrial cancer, mTOR signaling pathway, and VEGF signaling pathway." (PMID 35816294, 2022). "GSEA results showed that high expression of PKD1 was enriched in apoptosis, and low expression of PKD1 was enriched in B cell receptor signaling pathway, endometrial cancer, mTOR signaling pathway, and VEGF signaling pathway." (PMID 35816294, 2022).
Fabry disease (1 paper, 2023). Fabry disease (FD) is a progressive, inherited, multisystemic lysosomal storage disease characterized by specific neurological, cutaneous, renal, cardiovascular, cochleo-vestibular and cerebrovascular manifestations. "Successively, two relatives (one brother and a sister) were analyzed: the brother had both variants in GLA and PKD1 with a moderate renal impairment plus a cardiac and skin impairment from Fabry disease, while the sister had the PKD1 variant only." (PMID 37372416, 2023). "The authors described a 60-year-old male patient who was diagnosed with Fabry disease at 34 years of age and a VUS variant in PKD1." (PMID 37372416, 2023).
glioblastoma (1 paper, 2025). The most malignant astrocytic tumor (WHO grade IV). "Glioblastomas demonstrated the greatest increase in PKD1 and PKD2 expression compared to other grades of malignancy (p < 0.05)." (PMID 40299470, 2025). "However, the expression levels of PKD1 and PKD2 had no influence on the OS or PFS of glioblastoma patients." (PMID 40299470, 2025).
Granuloma (1 paper, 2024). A compact, organized collection of mature mononuclear phagocytes, which may be but is not necessarily accompanied by accessory features such as necrosis. "To determine whether PKD1 in myeloid lineage cells contributes to leukocyte infiltration and accumulation, and the development of granulomas in the lungs, we examined lung tissue sections from WT mice and PKD1mKO mice that had been repeatedly exposed to S. rectivirgula for 3 weeks." (PMID 39464896, 2024).
Graves disease (1 paper, 2023). Graves' disease is an autoimmune disorder that leads to overactivity of the thyroid gland (hyperthyroidism).It is caused by an abnormal immune system response that causes the thyroid gland to produce too much thyroid hormones. "Of the kinases analyzed, PKC (theta) and PKD1 in particular, showed differential activity in benign and malignant tumors, while oncocytic neoplasia or Graves’ disease contributed to erroneous classifications." (PMID 37760447, 2023).
head and neck cancer (1 paper, 2018). A primary or metastatic malignant neoplasm affecting the head and neck. "Taken together, these results indicated that PKD1 expression was frequently reduced in tumors of head and neck cancer patients." (PMID 30419840, 2018). "The frequent PKD1 downregualtion in HNSCC tumors and cell lines suggests a potential role of this protein in the pathogenesis of head and neck cancer." (PMID 30419840, 2018).
Horseshoe kidney (1 paper, 2025). A connection of the right and left kidney by an isthmus of functioning renal parenchyma or fibrous tissue that crosses the midline. "We reported a potentially pathogenic polycystin 1 (PKD1) gene in a patient with ADPKD and horseshoe kidney." (PMID 40507770, 2025).